NGF (nerve growth factor)
Diseases named in the same sentence as NGF in open-access papers (continued):
Sharing a sentence is not in itself a finding about the gene and the disease.
neurological diseases (52 papers, 2012 to 2025). "Glutamate-induced excitotoxicity is considered a common hallmark of many neurological disorders and has been linked to alterations in the expression of the neurotrophin nerve growth factor (NGF)." (PMID 35565989, 2022). "Endostatin has strong associations with neurological disease and can dose-dependently bind and sequester nerve growth factor (NGF) to prevent neurite outgrowth and migration in PC12 cells." (PMID 34772945, 2021). "Furthermore, dysregulation of NGF signaling has been associated with various neurological disorders characterized by neuroinflammation, such as Alzheimer’s disease, Parkinson’s disease, multiple sclerosis, and neuropathic pain conditions." (PMID 38392180, 2024). "Of the growth factors and neurotrophins, nerve growth factor (NGF) is of the greatest interest for the therapy of diseases of the nervous system." (PMID 40426873, 2025). "NGF was one of the first to be identified by Rita Levi-Montalcini, and it seemed that its clinical use would be beneficial in almost all neurological disorders." (PMID 41562905, 2025). "In the area of neurological disorders, NGF has been scrutinized for its potential in both neurodegenerative and non-neurodegenerative conditions." (PMID 40153582, 2024). "The therapeutic promise of NGF and other neurotrophic factors in addressing neurological diseases and conditions is widely acknowledged, underscoring their potential impact." (PMID 40153582, 2024). "NGF has been studied in neurological disorders such as hypoxic–ischemic encephalopathy, traumatic brain injury, neurobehavioral and neurodevelopmental diseases, congenital malformations, cerebral infections, and in oncological and ocular diseases." (PMID 39056738, 2024). "The study of NGF and neurotrophic factors continues to be an exciting area of research, enabling researchers to understand various neurological disorders and potential therapeutic interventions." (PMID 40153582, 2024). "The objective of this review is to provide a comprehensive summary of the most authoritative literature on the use of NGF as a potential therapeutic and prognostic element in neurological disorders along with exploring prospects in this field." (PMID 40153582, 2024). "After many years of investigation, it is indeed well established that aberrations and/or derangement of NGF signaling are involved not only in neurological disorders, but also in the pathogenesis of human proliferative diseases, including PC." (PMID 36941697, 2023). "In general, NGF-based production and treatment approaches have great potential for the treatment of neurological diseases." (PMID 38049878, 2023). "The neurotrophin Nerve Growth Factor (NGF) holds a great potential as a therapeutic candidate for the treatment of neurological diseases." (PMID 35360160, 2022). "Otherwise, mature NGF has been continuously tested for its use in neurological diseases and made good progress; however, in the central neural system, NGF therapy still confronted the big challenge of vector mistargeting and blood-brain barrier delivery." (PMID 35391929, 2022). "Altered mitochondrial biogenesis by NGF and abnormal mitochondrial dynamics have been implicated in the etiology and progression of ASD, as well as some of the more common neurological diseases associated with mitochondrial dysfunction." (PMID 36233217, 2022). "In neurological diseases, emodin directly protects nerve cells by regulating hormones, nerve growth factor (NGF), and related signaling pathways." (PMID 36225183, 2022). "A recent meta-analysis of randomized controlled trials testing intramuscular injection of NGF over ten years in China concluded positively about its safety and efficacy for the treatment of neurological diseases." (PMID 35928573, 2022).
neurological diseases (continued). "Because of its structural and functional characteristics, BBB “shuts down” several drugs used to treat neurological diseases, such as exogenous nerve growth factor (NGF), which becomes a major obstacle during treatment." (PMID 36313622, 2022). "The neurotrophin Nerve Growth Factor (NGF) has been suggested to play a neuroprotective factor in several neurological diseases and has been a matter of numerous basic and clinical research studies." (PMID 35360160, 2022). "Several drugs, including neutralizing antibodies, small inhibitors, and peptides have been synthesized to shut down the NGF circuit in neurological disorders (Longo and Massa, 2013 and references therein)." (PMID 34268306, 2021). "In preclinical models of neurological disease, NGF treatment reverses the effects of lesions and age-related degeneration of basal forebrain cholinergic neurons, including the recovery of learning and memory." (PMID 30443202, 2018). "NGF is an important molecule involved in the maintenance of numerous neuronal populations, and its alterations in metabolism are crucial for different neurological disorders." (PMID 28083536, 2016). "NGF levels can rise in many different conditions such as neurologic diseases, endocrinological disorders and diseases of the immune system." (PMID 26746899, 2016). "As the development of natural model NGF and β-NGF-cDNA cloned, exogenous NGF came to be an available therapeutic agent for neurological diseases." (PMID 27843750, 2016). "Neurotrophic factors such as neurotrophins, including NGF, were predicted to be suitable therapeutic tools for some neurological disorders or as supplements for brain health." (PMID 23554829, 2013). "Though applied to a wide spectrum of neurological and non-neurological diseases, clinical utilization of NGF, especially when systemically administered, remains hampered by important adverse events, such as those derived from the effects of NGF on pain system." (PMID 23190582, 2012). "In neurological disorders, bioactive factors such as nerve growth factor (NGF) promote stem cell differentiation into neural-like cells, while brain-derived neurotrophic factor (BDNF) and glial cell-derived neurotrophic factor (GDNF) enhance neurite outgrowth and Schwann cell function." (PMID 40710251, 2025). "NGF-based therapies for Neurological Diseases in human beings." (PMID 40153582, 2024). "Additionally, nerve growth factor has emerged as a significant therapeutic option for pediatric neurological diseases due to its ability to promote neuronal survival, repair, and plasticity." (PMID 39479375, 2024). "BDNF and NGF modulation are vital markers for treating or preventing neurologic diseases." (PMID 39628974, 2024). "NGF shows significant promise as a therapeutic candidate for neurological disorders." (PMID 39056738, 2024). "These innovative applications of NGF may overcome the limitations of current NGF therapies and pave the way for more effective and safer treatments for neurological diseases." (PMID 40153582, 2024). "In neurological disorders, NGF plays a key role in maintaining neuronal health and function." (PMID 39056738, 2024). "In addition, through extensive research on the BBB, connecting specific brain-targeting ligands with nanocarriers can not only increase the brain uptake of NGF but also minimize drug toxicity and enhance the therapeutic effect of neurological diseases." (PMID 38049878, 2023). "ProNGF is the prevalent form of NGF in the brains of AD patients and its processing into mature NGF may be impaired in neurological diseases." (PMID 34867367, 2021). "This raised the possibility that NGF and semaphorin family members could be combined, in the clinic, for treating of neurological diseases." (PMID 28098758, 2017). "Low levels of NGF in cerebrospinal fluid and a deficit of NGF signaling might provide the basis for the occurrence of these neurological diseases." (PMID 25250333, 2014).
neurological diseases (continued). "Similarly, NSCs stable-expressing neurotrophies, such as glial cell-derived neurotrophic factor (GDNF), brain-derived neurotrophic factor (BDNF), and NGF, exhibited remarkably improved proliferation, survival, and functional recovery in different neurologic disease animal models." (PMID 34135002, 2021). "Overall, this versatile neurophilic biomimetic lipoprotein represents a significant advancement in neurotrophin delivery, with potential applications extending beyond NGF to other therapeutic protein cargos for TBI and various neurological disorders." (PMID 40824134, 2025). "Collectively, this neurophilic biomimetic lipoprotein platform demonstrates broad potential for brain‐targeted delivery of neurotrophins beyond NGF, offering a promising translational strategy for TBI and related neurological disorders." (PMID 40824134, 2025). "Thus, exercise-induced enhancement of NGF within the septohippocampal pathway represents a key avenue for aiding failing septo-hippocampal functioning and therefore has significant potential for the recovery of memory and cognition in several neurological disorders." (PMID 30443202, 2018). "Accordingly, phase 1 clinical trials based on NGF gene delivery to NBM proved that this approach has the potential to improve cognitive symptoms and modify neurological disease progression in AD patients." (PMID 29163051, 2017). "Clinical trials are currently assessing the potential of NGF gene therapy for various neurological disorders, but the results have not been entirely convincing." (PMID 40153582, 2024). "In addition, BYHWD was shown to be able to alleviate neurologic disorders after injury by activating the Wnt/β-catenin signaling pathway and elevating the expression levels of BDNF and NGF." (PMID 36906602, 2023). "Neurotrophins, such as nerve growth factor (NGF) and brain-derived neurotrophic factor (BDNF), are known to play an important role in pre- and post-natal brain development, making them of great interest for the diagnosis and treatment of numerous neurological disorders." (PMID 36136675, 2022).
peripheral neuropathy (38 papers, 2009 to 2026). A disorder affecting the peripheral nervous system. "Anti-NGF mAbs alleviate the peripheral neuropathy caused by chemotherapeutic drugs such as paclitaxel, cisplatin and vincristine." (PMID 40783715, 2025). "We investigated the protective effect of maltol on neuromodulators in peripheral neuropathy and observed that maltol significantly enhanced the downregulation of NGF and Nrn1 caused by HG and PA." (PMID 39338303, 2024). "Alterations in calcium homeostasis, autoimmune inflammatory processes, and blockade of nerve growth factor (NGF) mediated neuronal survival have also been implicated in peripheral neuropathy induced by bortezomib." (PMID 35418856, 2022). "Peripheral neuropathy: Diabetic peripheral neuropathy is caused by many factors, such as oxidative stress, hypoxia, AGEs, activation of T lymphocytes and deficiency of nerve growth factor (NGF)." (PMID 34721299, 2021). "The results of the study demonstrated an association between increased NGF levels and patients developing painful chemotherapy-induced peripheral neuropathy (CIPN), whereas NGF levels remained stable in patients with either painless or absent CIPN." (PMID 34357136, 2021). "Some clinical trials have indicated that NGF is safe and effective as a treatment for preventing progression of diabetic or human immunodeficiency virus-associated peripheral neuropathies at the highest dose of 0.3 μg/kg two or three times per week." (PMID 31016359, 2019). "DBD was partly caused by DM-induced peripheral neuropathy with the reduced expression of NGF." (PMID 25974036, 2015). "This suggests that the diminished levels of NGF in epidermal keratinocytes contribute to the pathogenesis of peripheral neuropathy." (PMID 41139799, 2025). "When paclitaxel-induced peripheral neuropathy is treated with N-acetylcysteine or metformin, increased serum NGF levels are observed, along with the remission of paraesthesia and sensory loss." (PMID 40783715, 2025). "It is important to emphasize that studies on peripheral neuropathies have frequently used subcutaneous administration of NGF, with contrasting results." (PMID 40153582, 2024). "Some studies revealed a correlation between reduced NGF serum levels in diabetic patients and the clinical manifestation of peripheral neuropathy." (PMID 40153582, 2024). "By using an adipocyte-tropic adeno-associated virus (AAV) to deliver BDNF or NGF to subcutaneous white adipose tissue, the effects of BDNF and NGF on adipose tissue in combination to peripheral neuropathy was examined." (PMID 39194496, 2024). "Corroborating our findings, a decrease in NGF expression at the injury site has been shown in animals with peripheral neuropathy responsive to different therapeutic interventions." (PMID 37175503, 2023). "Neurofilament heavy chain, transmembrane protein serine 5, and nerve growth factor were significantly altered in patients with peripheral neuropathy compared with controls." (PMID 36574244, 2022). "Neurofilament heavy chain, transmembrane protease serine 5, and nerve growth factor were also significantly altered in peripheral neuropathy, although these results are based on few studies." (PMID 36574244, 2022). "In contrast, nerve growth factor was the only biomarker that showed a significant decrease in patients with peripheral neuropathy compared with controls (SMD, −1.38 [95% CI, −1.68 to −1.09]; P < .001; I2 = 98%), with considerable heterogeneity." (PMID 36574244, 2022). "The plasma NGF and exosome-related NGF will be detected in patients with diverse chemotherapy-induced peripheral neuropathy in our center population in BG01-1323L and in patients in the real-world experience of utidelone." (PMID 33163394, 2020). "Although the evidence of neuropathic pain with NGF is obvious, there are still trials for NGF treatment because it has great pharmacological potential for the treatment of central neurodegenerative diseases and for peripheral neuropathies." (PMID 26728069, 2016).
peripheral neuropathy (continued). "In cases of clinical trials with recombinant human NGF (rhNGF) on peripheral neuropathies, phase I trials have shown that dose-dependent mild to moderate muscle pain and hyperalgesia appeared at the injection site as a side effect." (PMID 26728069, 2016). "NGF, BDNF and NT-3 deficiencies have been correlated with severe peripheral neuropathy and death of the organism." (PMID 24312363, 2013). "Thus, any disturbance in NGF synthesis, transport, and utilization in peripheral neurons can give rise to the nerve dysfunction characteristic of peripheral neuropathies." (PMID 40153582, 2024). "The Authors concluded that a simply approach to investigate the role of NGF in human peripheral neuropathy could be the use of molecules with the ability to stimulate both synthesis and release of NGF at the proximity of damaged tissue." (PMID 27439311, 2016). "Preclinical evidences showed a significant reduction in Nerve Growth Factor (NGF) levels during OXA administration in rat, which was correlated with the onset of peripheral neuropathy." (PMID 34357136, 2021). "Erinacines show biological activities, including acting as stimulators of nerve growth factor (NGF) synthesis, suggesting it could be useful as a treatment for neurodegenerative disorders and peripheral neuropathy." (PMID 34069721, 2021). "Decrease of NGF levels was previously reported in patients with newly developed peripheral neuropathy, but exogenous NGF administration has not shown therapeutic effects for peripheral neuropathy, yet." (PMID 28827818, 2017). "Interestingly, the role of NGF in peripheral neuropathy is not simple." (PMID 28827818, 2017). "The endogenous production of neurotrophins such as NGF is essential for repair of central nervous system neurological damage, but its lack of permeability limits the exogenous use of NGF for a therapeutic purpose through the BBB and side effects such as peripheral neuropathies." (PMID 29955238, 2018).
psychiatric disorder (23 papers, 2012 to 2026). A disorder characterized by behavioral and/or psychological abnormalities, often accompanied by physical symptoms. "Associated with various mental illnesses, neurotrophins are the most studied subgroup of neurotrophic factors, a family including the nerve growth factor NGF, the brain-derived neurotrophic factor (BDNF), neurotrophin 3 (NT3) and neurotrophin 4 (NT4)." (PMID 40869374, 2025). "NGF exerts a trophic action and is implicated in cerebral alterations associated with psychiatric disorders." (PMID 33193575, 2020). "NGF codes for nerve growth factor that exerts a trophic action on the cholinergic neurons of the basal forebrain nuclei and is implicated in cerebral alterations associated with psychiatric disorders." (PMID 33193575, 2020). "According to research on the shared mechanism between psychiatric disorders and thyroid hormone disorders, fluctuations in the levels of neurotrophins, including NGF and BDNF, in thyroid dysfunction are similar to those observed in psychiatric disorders." (PMID 40308388, 2025). "In this network, BDNF and NGF are upstream of VGF and highly associated with psychiatric disorders and neurogenesis." (PMID 27877109, 2016). "Neuronal PAS domain protein 3 (NPAS3) and VGF (VGF Nerve Growth Factor (NGF) Inducible) are important for neurogenesis and psychiatric disorders." (PMID 27877109, 2016). "A consistent body of evidence demonstrates the clinical values of NGF and BDNF changes in serum by showing their correlation with the insurgence, severity, and response to treatments in neurological, immune, and psychiatric diseases." (PMID 37175781, 2023). "GSK3B, BDNF, NGF, NRG1, HTR2C, and PIP4K2A play important roles in molecular mechanisms of psychiatric disorders." (PMID 33193575, 2020). "Neurotrophins and their receptors have a nerve growth factor (NGF) which plays key roles in immune disorders, nerve cells growth and development, cardiovascular disorders, and psychiatric diseases." (PMID 35052649, 2022). "GSK3B, BDNF, NGF, NRG1, HTR2C, and PIP4K2A are genes that showed some importance in the study of the molecular etiology of psychiatric disorders." (PMID 33193575, 2020). "Particularly, disturbances of NGF and VEGF have been described in most psychiatric diseases and could therefore be especially suitable as indicators." (PMID 31827642, 2019). "NGF and VEGF are known to be involved in different psychiatric diseases." (PMID 31827642, 2019). "During development, the expression of NGF and BDNF has been localized to the hippocampus and prefrontal cortex, two regions which are well-studied sites of both developmental and adult synaptic plasticity and playing a key role in psychiatric disorders." (PMID 22474604, 2012).